POLQ (DNA polymerase theta)
Diseases named in the same sentence as POLQ in open-access papers (continued):
Sharing a sentence is not in itself a finding about the gene and the disease.
non-small cell lung carcinoma (5 papers, 2018 to 2025). A group of at least three distinct histological types of lung cancer, including non-small cell squamous cell carcinoma, adenocarcinoma, and large cell carcinoma. "POLQ is upregulated in oral squamous cell carcinomas, and higher expression of POLQ was associated with poor outcome in patients with early to mid-stage non small-cell lung cancers." (PMID 29301327, 2018). "As an example, in early- to mid-stage non-small cell lung cancer, Claspin was only one of a set of five genes (POLQ, PLK1, RAD51, CDC6, and CLSPN) encoding proteins involved in the maintenance of genome stability that were found to be consistently upregulated and associated with poor survival." (PMID 41009395, 2025). "In non-small cell lung cancer, POLQ upregulates DNA replication initiation proteins such as CDC6 and PLK1, enhancing tumor cell tolerance to replication stress, promoting cell proliferation, and resulting in poor prognosis." (PMID 38270643, 2024). "In addition, over-expression of POLQ, PLK1, RAD51, CDC6, and CLSPN was found to correlate with worse prognosis in non-small cell lung cancer." (PMID 41009395, 2025).
melanoma (4 papers, 2020 to 2025). A malignant, usually aggressive tumor composed of atypical, neoplastic melanocytes. "One emerging factor identified in a recent study of patient derived melanoma samples is DNA polymerase-theta (Pol θ or POLQ)." (PMID 40299938, 2025). "Colony-forming experiments also showed that the proliferation ability of melanoma cells was significantly reduced after POLQ knockdown." (PMID 38370403, 2024). "In summary, all patients affected with PDAC and melanoma in family 25-9-44 carried the DAB1, POLQ and FGFBP3 variants, whereas none of the healthy individuals carried all three variants." (PMID 34357098, 2021).
esophageal cancer (3 papers, 2018 to 2025). A primary or metastatic malignant neoplasm involving the esophagus. "Furthermore, miRNA-based biomarkers (e.g., miR-132-3p, miR-576-5p) correlate with radiosensitivity in esophageal cancer; glioblastoma genes like POLQ, PRIM1, and RPA1 are linked to radioresistance, while miR-153-3p overexpression enhances radiosensitivity." (PMID 40277781, 2025). "Despite the important roles that POLQ plays in various cancers, there have been few studies characterizing its functional role in esophageal cancers to date." (PMID 34206946, 2021). "The importance of POLQ, however, has yet to be elucidated in esophageal cancer." (PMID 34206946, 2021).
esophageal squamous cell carcinoma (3 papers, 2021 to 2023). Esophageal squamous cell carcinoma (ESCC) is a type of esophageal carcinoma (EC) that can affect any part of the esophagus, but is usually located in the upper or middle third. "One study suggested that POLQ inhibition and FANCD2 deficiency activate cGAS-STING in esophageal squamous cell carcinoma." (PMID 36976649, 2023). "Here, we aimed to determine the importance and functional role of POLQ in esophageal squamous cell carcinoma (ESCC)." (PMID 34206946, 2021). "The POLQ and/or FANCD2 KO esophageal squamous cell carcinoma (ESCC) cells had a considerably higher number of micronuclei." (PMID 35741863, 2022).
Fanconi anemia (3 papers, 2021 to 2023). Fanconi anemia (FA) is a hereditary DNA repair disorder characterized by progressive pancytopenia with bone marrow failure, variable congenital malformations and predisposition to develop hematological or solid tumors. "We identified multiple members of HRD, Fanconi Anemia pathways, and POLQ, a polymerase with a helicase domain important for G4 structure resolution." (PMID 33963218, 2021). "Double KO of POLQ and FANCD2, a DNA damage repair gene functioning in both Fanconi anemia and homologous recombination DNA damage repair pathways, significantly sabotaged cell proliferation in vitro as well as in vivo, as compared with either of these single KOs." (PMID 34206946, 2021).
leukemia (3 papers, 2021 to 2024). A malignant (clonal) hematologic disorder, involving hematopoietic stem cells and characterized by the presence of primitive or atypical myeloid or lymphoid cells in the bone marrow and the blood. "One study found that POLQ can protect leukemia cells from DNA damage caused by chemotherapy drugs." (PMID 39768855, 2024). "Altogether, our data indicate an association between POLQ independent MMEJ and clonal hematopoiesis and elucidate mutational mechanisms involved in the very first steps of leukemia evolution." (PMID 33911081, 2021). "In addition, the study showed that inhibitors of oncogenic tyrosine kinases (OTK) or DNA–protein crosslink (dpc)-inducing drugs, such as etoposide, enhanced the anti-leukemia effects of POLQ inhibitors both in vitro and in vivo." (PMID 39768855, 2024).
pancreatic adenocarcinoma (3 papers, 2022 to 2024). "This correlation between survival of patients with pancreatic adenocarcinoma and POLQ mRNA levels was also confirmed recently." (PMID 39435280, 2024). "To assess the prognostic potential of POLQ gene expression in patients with pancreatic adenocarcinoma, we conducted a survival analysis using Gene Expression Profiling Interactive Analysis (GEPIA)." (PMID 39435280, 2024). "Analysis of the relation between POLQ H-score and tumor characteristics in patients with pancreatic adenocarcinoma by uni and multivariate analysis for overall survival." (PMID 39435280, 2024). "The data obtained in this study analyzing tumor samples by IHC from a cohort of pancreatic adenocarcinoma patients, allowed us to show that there is a strong impact of POLQ expression in the outcome of patients with this type of tumors." (PMID 39435280, 2024).
cervical cancer (2 papers, 2023 to 2024). A primary or metastatic malignant neoplasm involving the cervix. "Finally, our investigation found that the Apigenin derivatives should be suggested as a novel compound against HPV-associated cervical cancer and the DNA polymerase theta." (PMID 37783745, 2023). "The initial literature study revealed the potent antimicrobial and anticancer properties of Apigenin, prompting the selection of its potential derivatives to investigate their abilities as inhibitors of human papillomavirus-associated cervical cancer and DNA polymerase theta." (PMID 37783745, 2023). "The effectiveness of Apigenin derivatives has been utilized in this current investigation as the proposed compounds for the novel treatments for HPV-associated cervical cancer and the DNA polymerase theta since there is no targeted therapy for them." (PMID 37783745, 2023).
diffuse large B-cell lymphoma (2 papers, 2020 to 2025). "In diffuse large B cell lymphoma patients, ATM mutations were the most frequently represented, affecting nearly 15% of patients, followed by POLQ which was mutated in 10.6%." (PMID 33214570, 2020).
lymphoma (2 papers, 2014 to 2017). A malignant (clonal) proliferation of B- lymphocytes or T- lymphocytes which involves the lymph nodes, bone marrow and/or extranodal sites. "Furthermore, knockdown of POLQ in mouse lymphoma cells increases their sensitivity to etoposide." (PMID 25409685, 2014).
ovarian tumors (2 papers, 2021 to 2023). "This is best illustrated by the requirement of POLQ for the survival of BRCA1/2 mutant cancer cell lines, and the upregulation of POLQ in BRCA1/2 deficient breast and ovarian tumors." (PMID 33750946, 2021). "Additionally, POLQ represents a specific vulnerability in tumors with mutations in DDR genes, particularly genes involved in HR DNA repair, and reduces cell viability in HR-deficient cells derived from breast and ovarian tumors." (PMID 36976649, 2023).
uterine cancer (2 papers, 2020). Primary or metastatic malignant neoplasm involving the uterine corpus and/or the cervix. "Since mutations in POLE confer increased disease free survival (DFS) in patients with uterine cancer, even in those patients with high-grade tumors, we investigated the prognostic role of POLQ and REV3L mutations in POLE mutant tumors." (PMID 32838755, 2020).
anemia (1 paper, 2021). A reduction in the number of red blood cells, the amount of hemoglobin, and/or the volume of packed red blood cells. "Also in the signature were genes encoding the DNA glycosylase NEIL3, Fanconi Anemia factors (FANCD2, UBE2T), the ubiquitin protein ligase UBE3B, and two specialized DNA polymerases, POLM and POLQ, involved in the non-homologous end-joining (NHEJ) pathways of DSB repair." (PMID 34067180, 2021).
endometrial cancer (1 paper, 2020). Primary or metastatic malignant neoplasm involving the endometrium (mucous membrane that lines the endometrial cavity). "Thirty six percent of colorectal, stomach and endometrial cancers with POLE mutations carried additional mutations in POLQ (E/Q), POLZ/REV3L (E/Z) or both DNA polymerases (E/Z/Q)." (PMID 32838755, 2020).
endometriosis (1 paper, 2021). The growth of functional endometrial tissue in anatomic sites outside the uterine body. "Whereas, in the differentially expressed gene analysis, the tumor related genes TEX41, POLQ, and FLT1 were highly expressed in the ectopic endometrial cell group of endometriosis, and the expression of tumor suppressor gene PLCD1 was down-regulated when compared with the control group." (PMID 33868805, 2021).
hearing loss (1 paper, 2025). "The discovery that methylation at the promoter regions of DNMT3A, UQCR11, POLQ, and SIGLEC5 has a protective effect against hearing loss suggests a multifaceted mechanism by which epigenetic regulation preserves auditory function." (PMID 40428348, 2025).
lentivirus infection (1 paper, 2021). Virus diseases caused by the Lentivirus genus. "POLQ knockdown HCC cell model (shPOLQ) was constructed along with the corresponding negative control (shCtrl) through lentivirus infection for loss-of-function study." (PMID 34517891, 2021).
lymph node metastasis (1 paper, 2019). "The findings of our present study revealed an association between POLQ protein overexpression and advanced pathologic stage/lymph node metastasis in LAC." (PMID 31137743, 2019).
metastatic disease (1 paper, 2024). "Thus, pharmacological inhibition of POLQ might be a potential strategy against metastatic disease by sensitized cancer cells to ferroptosis." (PMID 38575587, 2024).
pancreatic disease (1 paper, 2021). "A PCMS family carried pathogenic low-frequency variants in the DAB1, POLQ and FGFBP3 genes, with all three co-segregating with pancreatic disease." (PMID 34357098, 2021). "The present WGS, however, detected potentially pathogenic variants in the ATM, SUFU, DAB1, POLQ, MAP3K3, FGFBP3 and ACAD9 genes that co-segregated with pancreatic disease in single FPC families, and thus might predispose them to the disease." (PMID 34357098, 2021). "A new finding of the present study is that affected patients from one FPC family can carry identical germline variants in up to three different genes, e.g., DAB1, POLQ and FGFBP3 in family 25-9-44 or MAPK3 and ACAD9 in family 25-4-46, which segregate with pancreatic disease." (PMID 34357098, 2021).
pancreatic ductal adenocarcinoma (1 paper, 2023). An infiltrating adenocarcinoma that arises from the epithelial cells of the pancreas. "The authors used pancreatic ductal adenocarcinoma (PDAC) cell and mouse models characterized by HR-associated gene alterations and POLQ overexpression." (PMID 37259920, 2023). "Their study focuses on pancreatic ductal adenocarcinoma (PDAC), motivated by the observations that nearly a quarter of PDAC cases are associated with HR-associated gene alterations and that POLQ overexpression correlates with worse prognosis in two independent cohorts of PDAC patients." (PMID 37259920, 2023).
pancreatitis (1 paper, 2023). Inflammation of the pancreas. "They include DNA damage response and DNA repair genes (ATM, BRCA1, BRCA2, and POLQ), pancreatitis gene (SPINK1) and cell apoptosis gene (CASP8)." (PMID 37234870, 2023).
prostate carcinoma (1 paper, 2024). A carcinoma that arises from epithelial cells of the prostate gland. "To understand the molecular consequences of POLQ dysregulation, we evaluated the association of POLQ RNA abundance with known prostate cancer drivers and prognostic biomarkers in ICGC PRAD-CA." (PMID 39166898, 2024). "Integrating primary prostate cancer patient data, we pinpoint POLQ as a top candidate modulator of radioresistance beyond our model system." (PMID 39166898, 2024). "Genetic or pharmacologic inhibition of POLQ resensitized radioresistant prostate cancer cells and induced proteomic signatures detectable in primary prostate cancer." (PMID 39166898, 2024). "Integration of model system and primary prostate cancer patient molecular data identified POLQ (DNA Polymerase Theta) as a candidate radiosensitizer." (PMID 39166898, 2024).
prostate tumors (1 paper, 2024). "Collectively, we revealed a widespread association of POLQ with somatic and clinical features of prostate tumors that marked POLQ as the top radioresistance modulator candidate." (PMID 39166898, 2024). "To validate the 12-gene POLQ inhibition signature, we used transcriptomic and proteomic profiling of primary prostate tumors." (PMID 39166898, 2024).
renal cell carcinoma (1 paper, 2025). "Regarding DNA DSB repair, FTO promotes proliferation and regulates DNA damage in renal cell carcinoma cells through the expression of DNA polymerase θ (POLQ), a key protein involved in microhomology-mediated end joining." (PMID 40485587, 2025).
cancer (101 papers, 2010 to 2026). A tumor composed of atypical neoplastic, often pleomorphic cells that invade other tissues. "In cancer cells deficient in HR, both a PolQ inhibitor and RECQL4 knockdown effectively eliminated these HR-deficient cells." (PMID 39870799, 2025). "POLQ is overexpressed in cancer cells with deficient repair mechanisms to fill single-stranded gaps, allowing continued replication and proliferation of cancer cells." (PMID 40149342, 2025). "POLQ, expressed abnormally in many cancers, is a DNA repair enzyme linked to multiple types of cancer, and its overexpression is associated with a poor prognosis." (PMID 40181128, 2025). "POLQ, which is frequently overexpressed in many cancers and linked to a poorer prognosis, has garnered considerable attention from researchers due to its involvement in the double-strand break (DSB) repair pathway." (PMID 38575587, 2024). "This is a protein encoded by the POLQ gene and this pathway is crucial for some cancers with deficiencies in homologous recombination (HR), given their reported dependence on TMEJ for survival and tumor growth." (PMID 39435280, 2024). "HR-deficient cancers exhibit POLQ overexpression and are highly dependent on Pol θ for their viability." (PMID 37259920, 2023). "Here, our results also revealed that the VUS of MSH6 and POLQ suggested potentially different trends in association with cancer in women and men, respectively." (PMID 36896836, 2023). "Particularly, since most healthy cells seem to tolerate Pol θ deficiency, the synthetic lethality between POLQ inactivation and HR deficiency has inspired efforts to discover and develop Pol θ inhibitors as cancer therapeutics." (PMID 37259920, 2023). "Homologous recombination (HR)-deficiency induces a dependency on DNA polymerase theta (Polθ/Polq)-mediated end joining, and Polθ inhibitors (Polθi) are in development for cancer therapy." (PMID 38001070, 2023). "Polymerase theta (Pol θ, encoded by POLQ) is overexpressed by HR-deficient cancers and promotes cancer cell survival by mediating error-prone double-stranded break (DSB) repair and facilitating resistance against poly-ADP ribose polymerase inhibitor treatment." (PMID 37259920, 2023). "Given its low-fidelity, mutation-prone repair of double-strand breaks, POLQ has been observed to increase genomic instability in cancer cells." (PMID 36976649, 2023). "As POLQ is crucial to the survival of HR-deficient cells, it is an emerging target in cancer therapeutics." (PMID 36976649, 2023). "Our findings present what is, to our knowledge, the first evidence for POLQ inhibition activating cGAS-STING signaling in HR-deficient cancer." (PMID 36976649, 2023). "Homologous recombination-deficient cancers rely on DNA polymerase Theta (Polθ)-Mediated End Joining (TMEJ), an alternative double-strand break repair pathway." (PMID 35357490, 2022). "Authors of various studies claim that POLQ mRNA expression is upregulated in HR-deficient cancer cells." (PMID 36613762, 2022). "Depletion of POLQ in POLQ-dependent cancers (i.e., malignancies deficient in HR) leads to synthetic lethality." (PMID 35875060, 2022). "POLQ inhibitors are a promising cancer treatment strategy in which cancer cells use DNA repair gene mutations to reconnect their DNA repair network to compensate for survival." (PMID 36544763, 2022). "At present, POLQ inhibitors, which represent a valuable therapeutic strategy for a range of cancers associated with BRCA mutations, including PAAD, are in development for clinical use." (PMID 36353555, 2022). "POLQ was revealed to be synthetic lethal with DNA repair genes frequently mutated in cancer (such as ATM, ATR, BRCA1/2, FANCD2, Ku70, RAD52, RAD51C, TP53BP1) and extensive efforts for the development of Polθ inhibitors are made by several companies." (PMID 34201502, 2021). "Collectively, these in vitro findings suggest that FANCD2-deficient cancer cells are hypersensitive to inhibition of POLQ-mediated repair." (PMID 34206946, 2021).